WEE1 (WEE1 G2 checkpoint kinase)
Diseases named in the same sentence as WEE1 in open-access papers (continued):
Sharing a sentence is not in itself a finding about the gene and the disease.
cancer (continued). "In addition to that, all combination therapeutic approaches that enhance cancer cell sensitivity to WEE1 inhibitors are listed in detail in this review, hoping it can aid in the design of more effective clinical trials in the future." (PMID 40565165, 2025). "Upregulation of Wee1 is common to several cancers and it usually correlates to a poor prognosis." (PMID 39528354, 2025). "Considering the relevance of Kif18A for survival of aneuploid cancer cells and the potential therapeutic targeting of both Kif18A and Wee1, these findings could also be relevant for cancer therapy." (PMID 39610707, 2024). "However, significantly more trials have been conducted with the Wee1 inhibitor (MK1775/AZD1775) in different cancer types." (PMID 39272874, 2024). "Wee1 has been extensively studied as a therapeutic target for cancer treatment." (PMID 38166399, 2024). "WEE1 as an oncogene is highly expressed in various cancer types, including breast cancer." (PMID 39156700, 2024). "Our study presented here suggests that the Wee1 inhibitor MK-1775 may act by destabilizing the attachment between kinetochores and microtubules, and could serve as a basis for improving and developing Wee1-targeted cancer chemotherapy." (PMID 38166399, 2024). "Therefore, inhibition of WEE1 has been suggested as a potential strategy for cancer therapy, especially in combination with DNA damaging agents." (PMID 39273409, 2024). "The effectiveness of WEE1 inhibition in KRAS-mutant cancer may be related to replication stress (RS), a type of cellular stress that occurs when the DNA replication machinery encounters obstacles that inhibit DNA replication." (PMID 38776912, 2024). "Interestingly, WEE1 was upregulated in only 3/17 cancer types, whereas PKMYT1 elevated in 16/17 cancer types." (PMID 38992067, 2024). "The mechanism inferred from the results of this study is that depletion of WEE1 in cancer cells by WEE1 inhibitors promotes the cell cycle, despite the presence of DNA damage, and induces apoptosis, which may have an antitumor effect." (PMID 39335109, 2024). "As an oncogene, WEE1 promotes cancer cells to evade the effects of DNA damage and abnormal mitosis." (PMID 39156700, 2024). "Furthermore, we summarize the current predictive biomarkers employed to treat cancer with WEE1 inhibitors." (PMID 38231277, 2024). "Through phosphorylation of the CDKs, WEE1 plays a role in homologous recombination DNA repair, and because cell cycle and DNA damage repair pathways are frequently interrupted during tumor development, WEE1 inhibitors are effective cancer therapeutics." (PMID 38778091, 2024). "Given that Cdk1 is a key kinase that activates the SAC and that inhibiting Wee1 extends mitosis in a SAC-dependent manner, it can be hypothesized that combining Wee1 and Kif18A inhibition may potentiate therapeutic effectiveness against aneuploid cancers." (PMID 39610707, 2024). "The expression of WEE1 in cancer cells has dual biological roles." (PMID 39156700, 2024). "Thus, combining ATR with Chk1 inhibition can be a rational approach to overcoming resistance to Wee1 inhibition, and it has demonstrated a synergistic anti-tumor effect in multiple types of cancer cells." (PMID 37296592, 2023). "Given the rapid emergence of resistance to monotherapy in cancer, we investigated whether combination BRD4i with WEE1 or ATR inhibition would be a strategy to exploit ARID1A loss by targeting two critical pathways critical for survival." (PMID 37841875, 2023). "Inhibiting Wee1 activity may be a strategy for cancer radiation because Wee1 has been identified as a potential target for DSB repair." (PMID 37808268, 2023). "It has been reported that as malignant transformation is induced, WEE1 upregulation in cancer cells might promote tumorigenesis by maintaining the levels of genomic instability." (PMID 37374977, 2023).
cancer (continued). "Furthermore, Wee-1 is overexpressed in most cancer cells and phosphorylation of its immediate substrate (CDC2; CDK1) will halt cell cycle progression at the G2-M phase." (PMID 37633054, 2023). "WEE1 inhibitors can promote cell death of genomically unstable cancers as individual agents, and also have the potential to synergize with radiotherapy and other DNA-damaging chemotherapies by limiting S/G2/M phase checkpoint repair, enhancing chromosomal damage and mitotic catastrophe." (PMID 36831373, 2023). "Moreover, the silencing of Wee1 expression increases cell death, decreases metastasis, and sensitizes cancer cells to chemotherapy." (PMID 37296592, 2023). "In addition to promotion of DNA damage and cell death, inhibitor targeting proteins in DNA repair mechanism such as ATR and WEE1 also induce anti-tumor immune responses and sensitizes cancer cells to immunotherapy." (PMID 37087441, 2023). "WEE1, which regulates entry into mitosis, is an important therapeutic target in cancer." (PMID 36300618, 2023). "Furthermore, an overexpression of Ovcar4-BRD4-S leads to a generation of chemoresistant polyploid giant cells with cancer stem-like cell features, making this cell line a relevant model to study alternative treatment options such as Wee-1 inhibitors." (PMID 37705995, 2023). "Wee1 is upregulated in various cancers including breast cancer." (PMID 36923534, 2023). "Notably, WEE1 inhibitors such as adavosertib are tested in cancer treatment trials; however, WEE1-regulated phosphoproteomes and their dynamics have not been systematically investigated." (PMID 36632060, 2023). "Moreover, upregulation of PKMYT1 has been shown to promote resistance of cancer cells to WEE1 inhibition." (PMID 37325550, 2023). "Inhibition of WEE1 by AZD1775 has also been shown to induce p-S345-CHK1 by activating ATR in other cancer cells, which may circumvent the effectiveness of WEE1 inhibition." (PMID 37987002, 2023). "Therefore, insights into the mechanisms that determine the sensitivity to WEE1 inhibition in cancers, especially EOC, are still unclear." (PMID 36378528, 2023). "WEE1 is a kinase involved in cell cycle regulation and the DNA damage response and was also identified as a synthetic lethal partner specific to ATRX deficiency in cancer." (PMID 36497337, 2022). "In addition, cancer stem cells adopt high WEE1 expression as a protection mechanism against therapeutic agents." (PMID 36499000, 2022). "Since then several studies have shown that combining ionizing radiation with inhibition of Wee1 by AZD1775 increased cell death or clonogenic death of cells derived from a variety of cancers, including of the lung, breast, prostate, esophagus, cervix, liver, brain, and pancreas." (PMID 35251998, 2022). "Therefore, it is postulated that the expression of WEE1 allows cancer cells to repair DNA damage following chemo- or radiotherapy, develop resistance, and continue to proliferate." (PMID 36499000, 2022). "Importantly, our preclinical findings also illustrate how pharmacologic manipulation of key cell cycle regulators (CDK1 and/or CDK2) can potentially limit the efficacy of WEE1 inhibitors in cancer patients." (PMID 35315355, 2022). "Preclinical studies support the existing hypothesis that targeting other cancer-promoting pathway components (such as WEE1, MEK/MAPK, and PI3K) may enhance PARPis efficacy; in particular, while still preserving anti-tumor activity." (PMID 35326571, 2022). "Given that activation of WEE1 contributes to chemoresistance in different cancers, inhibition of WEE1 may be a possible anti-tumor treatment." (PMID 35191808, 2022). "Thus, CCNE1 mRNA expression is a patient selection biomarker for WEE1 inhibitor response in patients with cancer at the clinical level." (PMID 35315355, 2022).
cancer (continued). "Although it was known that inhibition of ATR, CHK1, and WEE1 reduces dNTP concentrations in cancer cells, our findings that ATR kinase activity is essential to limit dU contamination and that dT partially rescues ATRi-induced CD8+ T cell and cancer death are, in our view, unanticipated." (PMID 36130512, 2022). "Notably, Wee1 overexpression is a chemotherapy adaptive response that allows cancer cells to enhance DNA damage repair and thus survival, implying Wee1 is a critical function in the DNA damage repair process." (PMID 36575478, 2022). "WEE1 is a de facto pan-cancer essential gene associated with negative prognostic factors, including lymph node involvement, induction of metastasis, increased proliferation markers, and resistance to cancer treatments." (PMID 35902728, 2022). "Wee1 inhibition may thus provide treatment opportunities especially for patients, whose cancer has acquired resistance to platinum-based chemotherapy or PARP inhibitors." (PMID 36081565, 2022). "The extent to which high replication stress characterizes human PTCL is unknown, though our preliminary analysis of ALCL cell lines (a form of PTCL) suggests a degree of sensitivity of these cancers to ATR/CHK1/Wee1 inhibitors." (PMID 35510955, 2022). "This suggested that Wee1 plays a potential role in the regulation of KIT in GIST which may contribute to an anti-proliferative effect of Wee1 inhibition in this cancer." (PMID 35965531, 2022). "We further find the cell cycle drivers cyclin D1 (CCND1) and WEE1 to be repressed by AATK induction and identify the loss of AATK via epigenetic silencing as correlated to impaired overall patient survival in various cancers." (PMID 35902728, 2022). "In various cancer models, Wee1 inhibition promotes accumulation of cytosolic dsDNA, leading to activation of the cGAS-STING pathway, increased type I interferon target gene expression when delivered alone, as well as in combination with ATR inhibitors or immune checkpoint blockade." (PMID 36106115, 2022). "Additionally, inhibiting Wee1 not only triggers cell cycle arrest and suppresses the development of cancer cells but also enhances CML cell sensitivity to IM in vitro and in vivo." (PMID 36575478, 2022). "Several studies have reported that WEE1 is highly expressed in various cancer types." (PMID 35191808, 2022). "However, the effects of combined WEE1 and ATR inhibition in other cancer cell types and the mechanisms underlying the synergistic killing remain poorly understood." (PMID 34359691, 2021). "Actually, WEE1, a mitotic inhibitor kinase, participates in the regulation of the DNA damage repair pathway, and its therapeutic inhibition along with chemotherapy is currently under clinical trials investigation for cancer treatment." (PMID 34572861, 2021). "Therefore, cancer cells with defective G1 checkpoint, rely on G2 checkpoint for DNA repair and targeting WEE1 in these cells induce untimely mitosis and cell death." (PMID 34277427, 2021). "Importantly, preclinical studies have validated WEE1 inhibition as a viable therapeutic target in treating cancer, and CDC25A is also deemed as a suitable therapeutic target for cancer treatment, establishing βTrCP as a tumor suppressor." (PMID 33130827, 2021). "The top intracellular pathways of the 12 overlapping genes were associated with circadian rhythms and entrainment (Arntl, Cry2, Per2, Per3, Bhlhe41), the cell cycle (Cdkn1a, Wee1), the oxytocin signaling pathway (Cdkn1a, Rcan1), and transcriptional misregulation in cancer (Cdkn1a, Per2)." (PMID 33668521, 2021). "WEE1 is a protein kinase that is involved in cell cycle regulation and the DNA damage response and has been shown to be overexpressed in several types of malignant tumors." (PMID 34686198, 2021).
cancer (continued). "In fact, although the purpose of the majority of anti-cancer therapeutic strategies involves cell cycle arrest, Wee1 kinase inhibition triggers mitosis and induces genomic instability, driving cells to follow a replication cycle, with consequential apoptosis for mitotic catastrophe." (PMID 34639030, 2021). "Because Wee1 is considered as a potential therapeutic target in various types of cancers, further deep insights into the relationship between DNA replication and Wee1 activation would be crucial for developing cancer therapy utilizing Wee1 inhibition." (PMID 33148697, 2021). "Several studies using different cancer models suggest that PARPi-resistant tumors are strongly dependent on the ATR/CHK1/WEE1 pathway, and that inhibition of these kinases may restore PARPi sensitivity." (PMID 34439286, 2021). "In recent years, WEE1 has emerged as a promising target in cancer treatments." (PMID 33666372, 2021). "Aside from the reported use of siRNA for the inhibition of Wee1 expression in different cancer models, several pharmacological inhibitors were developed and validated, both as single agents or in combination with DNA damaging agents (chemotherapy/radiotherapy)." (PMID 34639030, 2021). "Targeting Wee1 with adavosertib has emerged as a novel strategy for cancer therapy." (PMID 34298699, 2021). "Degradation upon conjugation of AZD1775 to pomalidomide functioned in a CRBN and proteasome-dependent manner, creating the novel and notably low-dose mechanism by which Wee1 overexpression in cancer cells may be repressed." (PMID 34671620, 2021). "The development of WEE1 inhibitors such as AZD1775 has been promising in the treatment of cancer." (PMID 34686198, 2021). "In another study, it was shown that Wee1 inhibition strengthened the spindle assembly checkpoint and extended mitosis to enhance the apoptotic cell death effect of antimicrotubule cancer drugs such as paclitaxel in several cancer cells and primary human adult lymphoblastic leukemia cells." (PMID 34269904, 2021). "Indeed, cancer cells seem to be strictly dependent on the functionality of WEE1/PKMYT1 kinases to survive, especially those with alterations targeting the G1 checkpoint." (PMID 32958072, 2020). "Importantly, premalignant cells were comparably sensitive to Wee1 inhibition as the fully transformed HNSCC cancer cell lines and demonstrated comparable mitotic failures." (PMID 32047167, 2020). "Inhibition of WEE1 is emerging as a promising therapeutic strategy in cancer." (PMID 32195191, 2020). "Inhibition of Wee1 activity has been considered a potential avenue for cancer radiotherapy." (PMID 32355263, 2020). "However, the inhibition of WEE1 has captured more attention, and in fact, in the first half of 2020, more than 50 studies have been published investigating the role of WEE1 inhibitors in cancer." (PMID 33053746, 2020). "Taken together, cancer cells that are in S-phase or in G2-phase, enter mitosis prematurely by Wee1 inhibition, which leads to mitotic failure, in line with the cell cycle distribution upon Wee1 inhibition." (PMID 32047167, 2020). "Moreover, the residual tumor after Wee1 inhibitor consisted of a large fraction of platinum-sensitive cancer cells, which predicts that the subsequent platinum-based chemotherapy cycles will be effective." (PMID 31822719, 2019). "WEE1 is highly expressed in various cancer types, hence is an attractive target for cancer therapy." (PMID 30190546, 2019).
cancer (continued). "Our data support the speculation that these two types of compounds (especially Wee1 inhibitors, which are currently in use in cancer clinical trials) may be considered for MPM with a high S-score." (PMID 30902996, 2019). "Thus, inhibiting Wee1, alone or in combination with DNA damaging agents, can kill cancer cells by mitotic catastrophe, a tumor suppressive response that follows mitosis onset in the presence of under-replicated or damaged DNA." (PMID 31200459, 2019). "Although this mechanism was not tested in other cancer types, based on the fundamental role of WEE1 in cell cycle regulation we expect a similar association and response in other cell types." (PMID 31703356, 2019). "The increased efficacy seen with the addition of the Wee1 or CHK1 inhibitor suggests that this combination could be inducing mitotic catastrophe in cancer cells." (PMID 30629587, 2019). "TIMELESS depletion in combination with Wee1 or CHK1 inhibition causes an additive decrease in cancer cell metabolic capacity with limited effects in non-transformed human colon epithelial cells." (PMID 30629587, 2019). "Alternatively, combined inhibition of wee1, a protein kinase that regulates the G2 checkpoint in the cell cycle, with mTOR inhibition may selectively treat RAS-mutated cancer." (PMID 31277692, 2019). "The addition of a WEE1 inhibitor to olaparib may force cancer cells to proliferate in the presence of PARP1-mediated DNA damages resulting in a massive induction of cell death." (PMID 31717700, 2019). "Thus, the Wee1 inhibitor very effectively kills cancer cells with an active on-target resistance mechanism." (PMID 31822719, 2019). "Finally, we validated that WEE1 kinase inhibition can sensitize human HNSCC cancer cells to both direct and ADCC-mediated NK lysis." (PMID 29925431, 2018). "Apart from growth, Wee1 plays a critical part in cancer progression." (PMID 29977914, 2018). "Studies describing human cancers with increased Wee1 expression have been reported." (PMID 29343688, 2018). "Moreover, different cancer cells depend on the expression of WEE1 for survival as shown by the effectiveness of a selective WEE1 inhibitor." (PMID 30068368, 2018). "Wee1 blockade, an emerging anticancer therapy among a range of cancer types, can abrogate the G2/M checkpoint and force cancer cells with unrepaired DNA lesions to enter into unscheduled mitosis and undergo DNA damage-mediated cell death, namely, mitotic catastrophe." (PMID 29977914, 2018). "In this condition, Wee1 plays the role of a cancer-conserving oncogene and inhibition of its activity may be exploited to sensitize cells toward combinations with DNA-damaging therapy." (PMID 29343688, 2018). "Intriguingly, Wee1 blockade, especially in combination with genotoxic chemotherapies, is emerging as a new therapeutic strategy and has been subjected to various clinical trial investigations among a variety of cancers." (PMID 29977914, 2018). "Wee1 activity can be chemically inhibited by the small molecule MK-1775, which is currently being tested in phase I/II clinical trials in combination with other anti-cancer drugs." (PMID 29088738, 2017). "Similar effects have been reported in various cancer cell lines of different origin, including ovarian, melanoma, neuroblastoma, leukemia and lymphoma cells, suggesting that combined Chk1/Wee1 inhibition may be a promising approach for cancer treatment." (PMID 28030798, 2017). "We speculate that upregulated WEE1 and its role in conserving branching tube formation in the face of apoptotic pressures could be relevant to other cancers in which angiogenesis is a key player." (PMID 28178688, 2017). "Wee1 is reported to be overexpressed in several cancers including breast." (PMID 29088738, 2017). "Finally, we demonstrated that combined cisplatin treatment and WEE1 inhibition synergistically inhibits xenograft cancer growth accompanied by markedly reduced expression of TNBC signature genes." (PMID 28262781, 2017).